NCAPG (non-SMC condensin I complex subunit G)
Diseases named in the same sentence as NCAPG in open-access papers (continued):
Sharing a sentence is not in itself a finding about the gene and the disease.
tumor (continued). "As trastuzumab resistance results in higher tumor relapse rates of HER2+ BC20, we next assessed the expression of NCAPG in patients with different relapse status." (PMID 32683421, 2020). "In our pan-cancer analysis, in high-incidence tumor types such as BRCA, LUAD and LUSC, more than 50% of samples had overexpressed NCAPG expression." (PMID 32300299, 2020). "Gleason score, clinical tumor stage, lymph node involvement, margin status, NEK2, BUB1 and NCAPG in 9-genes cluster were significant by univariate Cox proportional hazard regression analysis." (PMID 31273254, 2019). "Knockdown of NCAPG induces HCC cell mitosis and inhibits cell growth, proliferation and migration in vitro and tetracycline-inducible shRNA knockdown of NCAPG inhibits tumor growth of HCC cells in vivo." (PMID 29467813, 2018). "In conclusion, NCAPG overexpression may promote EMT and inhibit tumor cell apoptosis by activating the Wnt/β-catenin signaling pathway." (PMID 37335105, 2023). "Furthermore, the tissue microarray containing 30 cases of non-tumor lung tissue samples and 60 cases of LUAD tissue samples were subjected to IHC experiment to assesses the expression level of NCAPG." (PMID 35254214, 2022). "We speculate that NCAPG might interact with LGALS1 to upregulate SPARC, leading to activate EMT signaling and augment tumor-derived vascular permeability." (PMID 35180865, 2022). "The results showed that the expression of NCAPG was tightly related with tumor size (P = 0.010) while not related with age, gender, and tumor grade (P > 0.05)." (PMID 35601741, 2022). "Recently, studies have shown that the up-regulation of Non-SMC Condensin I Complex Subunit G (NCAPG) in some tumors can promote tumor progression, and its high expression has a strong correlation with the poor prognosis of patients." (PMID 35254214, 2022). "Silencing NCAPG could markedly inhibit the proliferation, migration and invasion of LUAD cells in vitro, and inhibit tumor growth in vivo." (PMID 35254214, 2022). "NCAPG, also known as non-SMC condensin I complex subunit G, was positively associated with proliferation and migration in several tumor types." (PMID 35180865, 2022). "MAD2L1, NCAPG, PBK, and PLK4) was validated using qRT-PCR in MDA-MB-231 and BT-549.Taken together, our data highlighted activation of several tumor suppressor transcriptional regulatory networks in response to DNMT inhibition leading to tumor cell death." (PMID 34565361, 2021). "Both the levels of NCAPG mRNA and protein were remarkably increased in freshly collected BC tissues from patients with tumor relapse compared to patients without relapse." (PMID 32683421, 2020). "The positive expression levels of NCAPG were associated with differentiation levels, lymph metastasis, tumor, node (TNM), metastasis, and vascular invasion in patients (P < 0.05), but not with tumor site, tumor size, and preoperative CEA levels." (PMID 35292013, 2022). "Meanwhile, NCAPG overexpression can also increase the expression of MHCI and AMAD17 molecules, both of which are located on the tumor surface, thus, assisting in camouflaging the tumor and preventing NK cells from being activated in the immune microenvironment." (PMID 35992200, 2022). "Furthermore, we analyzed eight paired tumor and non-cancerous lung tissues to detect the expression of NCAPG." (PMID 34419073, 2021). "NCAPG is a member of non-SMC subunits in condensing I, which is involved in tumor cell survival, proliferation, migration, and metastasis." (PMID 35986371, 2022). "To validate the expression of ASMP, BUB1, CENPF, MAD2L1, NCAPG, SGO2, and TOP2A genes in tumor samples and adjoining nontumor samples, we measured their relative mRNA expressions using qPCR." (PMID 36072975, 2022). "However, it has not been reported whether the other four genes, NCAPG, S100A2, DERL3, and COL22A1, exert any biological role in the interaction between tumor and immune cells." (PMID 34136486, 2021).
cancer (49 papers, 2014 to 2025). A tumor composed of atypical neoplastic, often pleomorphic cells that invade other tissues. "First, in this study, the results of the meta-analysis showed that high expression of NCAPG is associated with poor prognosis, suggesting its role as a proto-oncogene in cancer." (PMID 36996493, 2023). "NCAPG protein is associated with chromosomal mitosis condensation and plays an imperative role in regulating cancer formation and growth." (PMID 37834394, 2023). "Previously, transcriptome analysis identified NCAPG as a possible key gene implicated in cancer cell stemness." (PMID 37553792, 2023). "Non-SMC condensin I complex subunit G (NCAPG) is a mitosis-associated chromosomal condensing protein that plays an important role in cancer progression." (PMID 35280743, 2022). "Previous studies have proved that the expression of NCAPG was tightly associated with the occurrence and development of several cancers." (PMID 35601741, 2022). "Studies in recent years have discovered that the NCAPG gene not only regulates the growth and differentiation of cancer cells but also influences muscular development in animals." (PMID 38473754, 2024). "We evaluated the NCAPG expression levels and performed a survival analysis in various cancers using the GEPIA2.0 database to validate our results." (PMID 36996493, 2023). "In conclusion, our study is the first to systematically address the prognostic and clinical significance of the NCAPG gene in cancer." (PMID 36996493, 2023). "The pooled results suggested that high NCAPG expression rates were correlated with worse OS in patients with different cancers (HR = 2.90, 95% confidence interval (CI) = 2.06–4.10, P < 0.00001)." (PMID 36996493, 2023). "We calculated the relationship between the expression of NCAPG and the annual survival rate of the cancer." (PMID 36996493, 2023). "Our results suggest that cancer patients with upregulated NCAPG expression have a 2.90-fold worse OS than those with low expression." (PMID 36996493, 2023). "Due to the existence of heterogeneity, a subgroup analysis was performed to further explore the impact of high NCAPG expression on survival in different types of cancer." (PMID 36996493, 2023). "Next, we verified the clinicopathological features of cancers with NCAPG expression using the UALCAN database." (PMID 36996493, 2023). "Second, it is necessary to fully verify and clarify the role and mechanism of NCAPG in cancer through cell models in vitro and in vivo." (PMID 36996493, 2023). "We provide meta-analytical and bioinformatic evidence that NCAPG acts as an oncogenic mRNA with great potential as a biological prognostic marker for cancer." (PMID 36996493, 2023). "The overall hazard ratio or odds ratio and 95% confidence intervals were calculated to assess the relationship between NCAPG expression and cancer survival prognosis or clinical characteristics." (PMID 36996493, 2023). "The results showed that upregulation of NCAPG was correlated with poorer overall survival (hazard ratio = 2.90, 95% confidence interval = 2.06–4.10, P < 0.001) in the cancers included in the study." (PMID 36996493, 2023). "NCAPG expression is increased in various cancers, including hepatocellular liver cancer, as an oncogene that stimulates cell proliferation and apoptosis through the PI3K/AKT/FOXO4 pathway." (PMID 35322101, 2022). "NCAPG has also spurred interest in being a possible anti-meiosis and mitosis target in cancer therapy, but little is known about, e.g., H2O2-mediated effects." (PMID 35063803, 2022). "We used two databases, Gene Expression Omnibus (GEO) and TCGA, to assess NCAPG expression in different types of cancers and their relationship with prognosis." (PMID 36238529, 2022). "We also investigated the immune correlation with NCAPG expression for 33 cancer types and subsequently found the strongest relationship for STAD." (PMID 36238529, 2022).
cancer (continued). "First, although bioinformatics provided useful insights into NCAPG expression in cancer, in vivo and in vitro biological experiments are required to validate our results to facilitate clinical applications." (PMID 36238529, 2022). "TYMSOS and NCAPG knockdown inhibited cell proliferation, cell migration, and cancer stem cell self-renewal in A549 cells." (PMID 35211508, 2021). "Above all, these findings confirm that NCAPG has distinct patterns of expression in different cancer tissues." (PMID 35211508, 2021). "Increasing evidence has demonstrated that nonstructural maintenance of chromosomes condensin I complex subunit G (NCAPG) plays a crucial role in the progression of human cancers." (PMID 35211508, 2021). "Taken together, these results confirm that NCAPG plays a crucial role in carcinogenesis of the human cancer." (PMID 35211508, 2021). "Next, we utilized the Oncomine database to examine the differences in expression of NCAPG in various cancers." (PMID 35211508, 2021). "We revealed that NCAPG was up-regulated in different cancers and positively correlated to poor prognosis in NSCLC." (PMID 35211508, 2021). "It has been shown that elevated NCAPG level promotes cancer cell migration by activating Wnt/β-catenin signaling." (PMID 35211508, 2021). "Downregulation of NCAPG by miR-99a-3p inhibits cancer cell aggressiveness via decreasing cell proliferation, migration, and invasion in castration-resistant prostate cancer." (PMID 32300299, 2020). "NCAPG8 is a novel mitotic gene for cell proliferation and migration, which has been less well studied in cancers, and a recently study demonstrated that NCAPG over expressed in GBMs and promote cell proliferation." (PMID 30867991, 2019). "Beyond its role in cancer biology, NCAPG has attracted attention in livestock genetics." (PMID 41056441, 2025). "Therefore, we performed a meta-analysis to explore the relationship between NCAPG upregulation and the clinical characteristics of cancer, analyze the prognostic value of NCAPG for cancer patients, and validate its role by bioinformatics methods." (PMID 36996493, 2023). "The results showed that NCAPG might be a potential prognostic marker for cancers of the respiratory, digestive, and other systems." (PMID 36996493, 2023). "Galectin-1 (Gal1) and non-SMC condensin I complex, subunit G (NCAPG) are associated with metastasis in several malignant tumors." (PMID 37335105, 2023). "Therefore, NCAPG can serve as a human cancer therapeutic target and a new potential prognostic biomarker." (PMID 36996493, 2023). "A human cancer meta-analysis suggests that NCAPG has a relationship with cell differentiation." (PMID 37893897, 2023). "However, none have combined meta-analytical and bioinformatics approaches to systematically assess the role of NCAPG in cancer." (PMID 36996493, 2023). "Previous researches have found that NCAPG was related tightly with the occurrence and progression of serious cancers and might provide a sensitive diagnosis-related biomarker for several cancers." (PMID 35601741, 2022). "The role of NCAPG in the progression and proliferation of various cancers has been confirmed." (PMID 35601741, 2022). "The condensation complex gene non-SMC condensin I complex subunit G(NCAPG), a cell cycle-associated condensin, is over-expressed in various cancers." (PMID 35292013, 2022). "This suggests that continuing to develop inhibitors targeting key protein molecules in these pathways may prolong the survival time of cancer patients with high expression of NCAPG, and restore the sensitivity of tumors to drug treatment." (PMID 35254214, 2022). "Aberrant expression of NCAPG has been elucidated in various human cancers." (PMID 35211508, 2021). "We found that NCAPG was highly expressed in various human cancers, especially in NSCLC." (PMID 35211508, 2021). "Here, we utilized diverse public databases to analyze the expression of NCAPG in pan-cancer." (PMID 35211508, 2021).
cancer (continued). "In addition, we also found significant correlations of NCAPG with immune infiltration and immune inhibitors across human heterogeneous cancers." (PMID 35211508, 2021). "NCAPG plays key roles in mitotic chromosome condensation and cancer progression." (PMID 35211508, 2021). "Furthermore, alterations in the associated genes (CDK-1, CDK-4, CCNE1, CDKN2A, RBI, NCAPG, AURKA, and CCND2) were determined in five CRC studies (CRC, TCGA, Firehose, CRC, TCGA, Nature, CRC, Pan-Cancer, MSKCC and CPTAC-2)." (PMID 33732631, 2021). "NCAPG was highly expressed in The Cancer Genome Atlas (TCGA) database, which includes the transcriptomes of 6,647 cancer and 647 normal tissue samples from 16 cancer types." (PMID 32300299, 2020). "When NCAPG was constitutively suppressed, cell division was significantly inhibited because the cancer cells take a much longer time to condense and decondense chromosome before and after nuclear division through a backup NCAPG-independent mechanism that is much less efficient." (PMID 31022357, 2019). "Therefore, exploring the molecular mechanism behind NCAPG's cancer-promoting effects and its role in chromosome condensation in EC could lead to develop novel targeted therapy strategies against cancer cell mitosis." (PMID 39744480, 2025). "In addition, upregulation of NCAPG can activate multiple signaling pathways to promote cell proliferation and anti-apoptotic activity and regulate DNA replication and mismatch repair in different cancer types." (PMID 36996493, 2023). "We performed a comprehensive evaluation of the pan-cancer potential of NCAPG as a predictive biomarker and identified its significant value in STAD, which may have implications for immunotherapy and is expected to provide a useful assessment system for clinical application." (PMID 36238529, 2022). "Furthermore, we check the level of NCAPG in TCGA pan-cancers using the GEPIA tool." (PMID 35211508, 2021). "Furthermore, NCAPG expression was upregulated in most cancers." (PMID 34419073, 2021). "All these studies indicated that NCAPG might exert a pivotal function in human cancers." (PMID 35211508, 2021). "Therefore, NCAPG is a promising target for cancer therapy across cancer types." (PMID 32300299, 2020). "Interestingly, NCAPG up-regulation is also observed in most of the 34 cancer types in the TCGA database, suggesting the possibility of targeting NCAPG as a generic cell cycle target to treat a broad range of cancers." (PMID 31022357, 2019). "In order to explore the specific downstream mechanism by which NCAPG promotes cancer, our study first employs ATAC-Seq to identify the open chromatin regions affected by NCAPG." (PMID 39744480, 2025). "NCAPG, NCAPH and ASPM have strong positive correlations with NCAPD2 expression in different cancers, especially in THYM." (PMID 38172945, 2024). "Therefore, we concluded that NCAPG may be a good prognostic indicator of various cancers." (PMID 36996493, 2023). "We figured out the TMB and MSI of every sample in human cancer and then examined the relevance between NCAPG expression and TMB, and MSI in various human cancers." (PMID 35211508, 2021). "To examine the expression of NCAPG in various cancers, we applies the TIMER database to analyze the expression of NCAPG in human cancer." (PMID 35211508, 2021). "The Cancer Genome Atlas (TCGA) data analysis displayed that NCAPG was markedly upregulated in BC tissues, particularly in HER2+ cancer tissues (P < 0.001)." (PMID 32683421, 2020). "YCG1/NCAPG and SMC2/SMC2 are components of the condensin complex, which are overexpressed in cancer." (PMID 31660150, 2019). "Using publicly available patient derived datasets obtained from TCGA, we determined that all eight condensin genes (SMC2, SMC4, NCAPD2, NCAPD3, NCAPG, NCAPG2, NCAPH, and NCAPH2) are frequently altered in at least 12 common cancer types." (PMID 31357676, 2019).
cancer (continued). "So far, validated targets of mir-21 included programmed cell death 4 gene (PDCD4), tropomyosin 1 (TPM1), phosphatase and tensin homolog (PTEN), chromosome condensation protein G (NCAPG), reticulon 4 isoform A (RTN4) and other cancer-related genes." (PMID 25098165, 2014). "The mechanism of NCAPG in cancer cell stemness is not yet clear, and thus clarifying molecular mechanism of NCAPG in LUAD progression is indispensable for therapy." (PMID 37553792, 2023). "Nonstructural maintenance of non-SMC condensin I complex subunit G (NCAPG) exerts critical effects on cancer progression." (PMID 36238529, 2022). "Non-SMC condensin I complex subunit G (NCAPG), a member of the subunit of condensin complex, is significantly overexpressed in various cancers and involved in the pathogenesis of cancers." (PMID 35986371, 2022). "In the ERBB2 network, we also found a subnetwork of direct protein–protein interactions formed by the non-SMC condensin I complexes (NCAPD2, NCAPG, NCAPH), a vital complex associated with the ERBB2 signaling pathway and cancer development." (PMID 33424936, 2020). "However, no studies have explored the mechanism by which NCAPG promotes cancer and whether it has the same effect in vivo." (PMID 39744480, 2025).
kidney disease (1 paper, 2022). "Among these four genes, NCAPG, NUP93, and TOP2A, were previously reported to be closely related to kidney disease." (PMID 35211510, 2022). "Among these four genes, NCAPG, NUP93, and TOP2A were previously reported to be closely related to kidney disease, such as ccRCC." (PMID 35211510, 2022).
NCAPG also shares sentences with these, for which no sentence is quoted: bladder cancer (4 papers); multiple myeloma (4); esophageal cancer (3); glioblastoma (3); adenocarcinoma (2); head and neck cancer (2); lung squamous cell carcinoma (2); pancreatic cancer (2); rectum adenocarcinoma (2); Azoospermia (1); bladder urothelial carcinoma (1); breast adenocarcinoma (1); cervical cancer (1); colon adenocarcinoma (1); diffuse large B-cell lymphoma (1); esophageal squamous cell carcinoma (1); Ewing sarcoma (1); Fanconi anemia (1); fibrosarcoma (1); head, neck squamous cell carcinoma (1); Idiopathic Pulmonary Hypertension (1); lymphoid neoplasm (1); lymphoma (1); Malignant Fibrous Histiocytoma (1); metastasis (1); myxofibrosarcoma (1); oral squamous cell carcinoma (1); ovarian serous cystadenocarcinoma (1); pleomorphic liposarcoma (1); primary immunodeficiency (1).
A further 7 diseases each share a sentence with NCAPG in 1 paper.